DDHD1 (DDHD domain containing 1)
Description:
Phospholipase A1 (PLA1) that hydrolyzes ester bonds at the sn-1 position of glycerophospholipids producing a free fatty acid and a lysophospholipid (Probable). Prefers phosphatidate (1,2-diacyl-sn-glycero-3-phosphate, PA) as substrate in vitro, but can efficiently hydrolyze phosphatidylinositol (1,2-diacyl-sn-glycero-3-phospho-(1D-myo-inositol), PI), as well as a range of other glycerophospholipid substrates such as phosphatidylcholine (1,2-diacyl-sn-glycero-3-phosphocholine, PC), phosphatidylethanolamine (1,2-diacyl-sn-glycero-3-phosphoethanolamine, PE), phosphatidylserine (1,2-diacyl-sn-glycero-3-phospho-L-serine, PS) and phosphatidylglycerol (1,2-diacyl-sn-glycero-3-phospho-(1'-sn-glycerol), PG) (Probable). Involved in the regulation of the endogenous content of polyunsaturated PI and PS lipids in the nervous system. Changes in these lipids extend to downstream metabolic products like PI phosphates PIP and PIP2, which play fundamental roles in cell biology (By similarity). Regulates mitochondrial morphology. These dynamic changes may be due to PA hydrolysis at the mitochondrial surface. May play a regulatory role in spermatogenesis or sperm function.
Synonyms: PA-PLA1; KIAA1705; iPLA1alpha; PAPLA1; iPLA1α; SPG28; iPLA1I
Tractability: PROTAC: ubiquitination databases record sites on it; its protein half-life has been measured.
Gene: Protein-coding gene on chromosome 14 (53,036,745 to 53,153,353, reverse strand). Ensembl gene ENSG00000100523.
Subcellular location: Cytoplasm
Pathways (Reactome):
Metabolism: Synthesis of PA
Gene Ontology:
Molecular function: protein binding; phospholipase activity; metal ion binding; phospholipase A1 activity
Biological process: positive regulation of mitochondrial fission; phosphatidylinositol metabolic process
Cellular component: cytosol; cytoplasm
Genetic constraint (gnomAD): Loss-of-function variants: 42 observed, 84.59 expected, observed/expected ratio (o/e) 0.5, 90% interval 0.39 to 0.64. The upper end of that interval is the gene's LOEUF score, 0.64, which puts it in group 2 of 6, group 1 being the genes least tolerant of losing a copy. Missense variants: 1,067 observed, 1,133.1 expected, observed/expected ratio (o/e) 0.94, 90% interval 0.89 to 0.99. Synonymous variants: 434 observed, 436.87 expected, observed/expected ratio (o/e) 0.99, 90% interval 0.92 to 1.08.
Gene-disease validity (ClinGen):
ClinGen rates the evidence that DDHD1 causes each of these diseases.
hereditary spastic paraplegia (autosomal recessive): Definitive. Hereditary spastic paraplegias (HSP) comprise a genetically and clinically heterogeneous group of neurodegenerative disorders characterized by progressive spasticity and hyperreflexia of the lower limbs.
Homologues: Orthologues: chimpanzee DDHD1 (99% identical), macaque DDHD1 (99% identical), pig DDHD1 (91% identical), rabbit DDHD1 (91% identical), rat Ddhd1 (90% identical), mouse Ddhd1 (89% identical), dog DDHD1 (87% identical), guinea pig DDHD1 (73% identical), tropical clawed frog ddhd1 (63% identical), zebrafish ddhd1b (55% identical), zebrafish ddhd1a (54% identical), Caenorhabditis elegans ipla-1 (28% identical). Paralogues in human: SEC23IP (23% identical), DDHD2 (20% identical).
Diseases named in the same sentence as DDHD1 in open-access papers:
DDHD1 is named in the same sentence as 20 diseases in open-access papers, as found by Europe PMC text mining. Sharing a sentence is not in itself a finding about the gene and the disease. The quoted sentences say what the papers report.
hereditary spastic paraplegia (9 papers, 2015 to 2024). "The DDHD1 (DDHD Domain Containing 1) gene is implicated in a rare neurological disorder termed hereditary spastic paraplegia (HSP) subtype 28 (SPG28) in humans." (PMID 39570887, 2024). "A recent study has reported that variants in DDHD1 are associated with hereditary spastic paraplegia and ASD74, and patients show clinical features such as cerebellar impairment, axonal neuropathy, distal sensory loss, and/or mitochondrial impairment." (PMID 33895774, 2021). "Mutations in DDHD1 are found in patients with hereditary spastic paraplegia; CDKN3 is linked with different cancers while for FERMT2 and CNIH, no human diseases have been described." (PMID 27757173, 2016). "Human genetic studies revealed that one of the causative mutations of hereditary spastic paraplegia (HSP) occurs in the DDHD1 gene (SPG28)." (PMID 32850804, 2020). "Genetic mutations in DDHD1, an intracellular PLA1, result in hereditary spastic paraplegia (HSP) in humans." (PMID 34089703, 2021). "Mutations in the phospholipase A1 family members DDHD1 and DDHD2 have recently been linked to autosomal-recessive forms of hereditary spastic paraplegia (HSP)." (PMID 25691889, 2015).
Spastic paraplegia (4 papers, 2017 to 2024). Complete loss of the ability to move the lower limbs accompanied by spasticity of the lower limbs. "In the case of DDHD1, deleterious mutations are responsible for a very rare recessive hereditary spastic paraplegia, SPG28." (PMID 39125098, 2024). "However our findings on the role of a wild type DDHD domain in preventing retinal degeneration provide an insight into the cellular mechanisms that could explain the neurodegenerative phenotype seen in spastic paraplegias, in patients carrying mutations in human DDHD1 and DDHD2." (PMID 33597200, 2021).
colon cancer (3 papers, 2018 to 2020). "Our recent study demonstrates that the anticancer effects induced by lemon nanovesicles on colon cancer cells are associated with a downregulation of the phospholipase DDHD1." (PMID 29653539, 2018). "Our previous study demonstrates that Citrus-limon derived nanovesicles are able to decrease colon cancer cell viability, and that this effect is associated with the downregulation of the intracellular phospholipase DDHD domain-containing protein 1 (DDHD1)." (PMID 29653539, 2018). "In our study, DDHD1 was identified as a potential target of miR-106a-5p in colon cancer cells, which influences disease progression." (PMID 32571262, 2020). "Studies have also demonstrated that the inhibition of the MAPK/ERK and PI3K/Akt signaling pathways reduce the viability of colon cancer cells in vitro, and apoptotic cell death is increased by the silencing of DDHD1 via small interfering RNA." (PMID 32571262, 2020). "In conclusion, this study provides the first evidence confirming the role of DDHD1 in cancer, providing a possibility to define a new target to design more effective therapies for colon cancer patients." (PMID 29653539, 2018). "In conclusion, this study provides the first evidence confirming the role of DDHD1 in cancer, providing the possibility to define a new target to design more effective therapies for colon cancer patients." (PMID 29653539, 2018). "In this study we were able to prove for the first time that DDHD1 supports colon cancer cell proliferation and survival." (PMID 29653539, 2018). "Stefania Raimondo showed that intracellular phospholipase A1 family member DDHD1 supports colon cancer cell proliferation and survival by modulating PI3K/Akt and ERK signaling pathways, which can be repressed with siRNAs against DDHD1." (PMID 30338239, 2018). "We found that the overexpression of DDHD1 in human colon cancer cells enhances in vitro and in vivo tumor growth, while its downregulation reduces in vitro colon cancer cell viability and increases apoptosis rate." (PMID 29653539, 2018). "In order to investigate the role of DDHD1 in colon cancer, the first approach was to use a small interference RNA." (PMID 29653539, 2018). "We demonstrated that silencing of DDHD1 by small interference RNA reduces in vitro colon cancer cell viability and increases apoptotic cell death through the inhibition of MAPK/ERK and PI3K/Akt signaling pathways." (PMID 29653539, 2018). "The results indicate that DDHD1 supports colon cancer cell proliferation and survival, since its downregulation reduces in vitro colon cancer cell viability and increases apoptosis rate, without affecting normal cells." (PMID 29653539, 2018). "In conclusion, for the first time our results show that DDHD1 is responsible for colon cancer cell growth, even though future studies will be needed in order to better understand and clarify the mechanism by which it acts on neoplastic transformation." (PMID 29653539, 2018). "Interestingly, in our previous study we found that the anti-cancer effects of Citrus-limon nanovesicles on colon cancer cells was related to the downregulation of proteins involved in lipid metabolism, including DDHD1." (PMID 29653539, 2018). "Moreover, DDHD1 supports the proliferation and survival of colon cancer cells." (PMID 32571262, 2020). "The chr22-38_28785274–29,006,793.1–miR-106a-5p-DDHD1 and chr22-38_28785274–29,006,793.1–miR-4319-GRHL1 axes may be related to CD4+ and CD8+ T cell infiltration in colon cancer." (PMID 32571262, 2020).
colorectal cancer (3 papers, 2018 to 2023). A primary or metastatic malignant neoplasm that affects the colon or rectum. "We found that the DDHD1-siRNA complex TNVs were able to deliver DDHD1-siRNA to human colorectal cancer cells, inhibiting the target expression by about 60%." (PMID 38203716, 2023). "Once we assessed that the TNVs were able to successfully transfer siRNAs into the target cells, we tested the function of siRNA-TNV complex on the modulation of DDHD1 in colorectal cancer cells." (PMID 38203716, 2023). "To test the possibility of using TNVs as natural nanovehicles for drug delivery, we selected the siRNA for DDHD1 since we previously reported that DDHD1 is involved in colorectal cancer cell proliferation and survival." (PMID 38203716, 2023). "Quantitative proteomics using SWATH-MS was performed to determinate the molecular effects induced by DDHD1 silencing in colorectal cancer cells." (PMID 29653539, 2018). "In vitro and in vivo assays were performed to investigate the functional role of DDHD1 in colorectal cancer cell growth." (PMID 29653539, 2018). "DDHD1 siRNAs and an overexpression vector were transfected into colorectal cancer and normal cells to downregulate or upregulate DDHD1 expression." (PMID 29653539, 2018).
Ataxia (2 papers, 2021 to 2023). Ataxia refers to impaired coordination of voluntary muscle movement. "However, our previous neurological examination has confirmed no signs of cerebellar ataxia in the SPG28 patient in the original pedigree, indicating there is no involvement of cerebellum in the gait disturbance we observed in Ddhd1 KO mice." (PMID 33600578, 2021).
amyotrophic lateral sclerosis (1 paper, 2020). Amyotrophic lateral sclerosis (ALS) is a neurodegenerative disease characterized by progressive muscular paralysis reflecting degeneration of motor neurons in the primary motor cortex, corticospinal tracts, brainstem and spinal cord. "Recent studies have revealed that mutations in the PA-PLA1/DDHD1 gene cause HSP and amyotrophic lateral sclerosis." (PMID 32850804, 2020).
distal myopathy (1 paper, 2021). Distal myopathy refers to a group of muscle diseases which share the clinical pattern of predominant weakness and atrophy beginning in the feet and/or hands. "Other allelic neurological disorders with the same gene associations are ataxia with oculomotor apraxia (SETX), HSP (ALS2, SPG11, ERLIN1, and DDHD1), JPLS (ALS2), dHMN (SIGMAR1), distal myopathy (GNE), and distal SMA (BICD2)." (PMID 34946884, 2021).
cancer (3 papers, 2016 to 2020). A tumor composed of atypical neoplastic, often pleomorphic cells that invade other tissues. "Additionally, we found that functional categories, significantly affected by DDHD1 silencing, were specifically related to cancer phenotype and for the first time associated to DDHD1 activity." (PMID 29653539, 2018). "As a phosphatidic acid (PA)-preferring PLA1 (PA-PLA1), intracellular DDHD1 has been studied extensively owing to its implications for cancer development." (PMID 32571262, 2020). "In this study we provide the first evidence of the involvement DDHD1 in cancer, elucidating its role in supporting tumor cell proliferation and survival." (PMID 29653539, 2018). "Therefore, further studies will be necessary to better understand and outline DDHD1 enzymatic activity in cancer, as well as its interaction with other proteins." (PMID 29653539, 2018). "Interestingly, the pathway/GO term analysis revealed that most of the functional categories negatively modulated by DDHD1 silencing were specifically related to a cancer phenotype." (PMID 29653539, 2018). "In addition, since the enzymatic activity of DDHD1 is correlated to the release of lysophospholipid mediators, known to be involved in the proliferation of cancer cells, we used the conditioned medium from DDHD1-expressing cells to treat DDHD1- silenced cells." (PMID 29653539, 2018). "Interestingly, the anti-cancer effects observed after nanovesicle treatment correlate to the downregulation of the phospholipase DDHD1." (PMID 29653539, 2018). "Additionally, DDHD1 overexpression supports in vitro and in vivo cancer cell growth." (PMID 29653539, 2018). "Although a possible involvement of DDHD1 in the LPI-GRR55 axis has been previously postulated, information about the involvement of the phospholipase in cancer is missing." (PMID 29653539, 2018). "While few studies are currently available on the contribution of DDHD1 in neurological disorders, there is no information on its role in cancer." (PMID 29653539, 2018). "Both DDHD1 mRNA and protein levels decreased in cancer as well as in non-tumor cells after siRNA transfection." (PMID 29653539, 2018). "The intracellular DDHD1 is a phosphatidic acid (PA)-preferring PLA1 (PA-PLA1) involved in the synthesis of lysophospholipid mediators such as LPI, which has been extensively studied for its implication in cancer development." (PMID 29653539, 2018). "We transiently transfected SW480 and HCT-116 cancer cell lines, as well as non-tumor cell lines HS5 and HUVEC, with scrambled (negative control) or DDHD1 siRNA and analyzed them after 48 and 72 h." (PMID 29653539, 2018).
tumor (2 papers, 2018 to 2020). "Our results were consistent with those of previous studies, which supported the effects of the lysophospholipid mediator DDHD1 on tumor processes." (PMID 32571262, 2020). "In order to better define the biological role of DDHD1 in tumor cells, we performed a quantitative proteomic analysis on DDHD1 silenced cells." (PMID 29653539, 2018). "Overall, the results of our study, together with the observation that DDHD1 silencing doesn’t affect normal cells, allow us to suggest DDHD1 as a possible target for the development of anti-tumor therapies." (PMID 29653539, 2018). "In addition, we demonstrate that DDHD1 acts on tumor cells by modulating PI3K/Akt and ERK signaling pathways." (PMID 29653539, 2018). "Gene and protein expression analyses on tumor biopsies show an increase of the pro-angiogenic cytokine IL8 and of the anti-apoptotic gene Survivin, confirming the increased trend of ERK1/2 phosphorylation after DDHD1 overexpression." (PMID 29653539, 2018).
DDHD1 also shares sentences with these, for which no sentence is quoted: neurological disorders (3 papers); paraplegia (2); axonal neuropathy (1); cerebellar ataxia (1); colon adenocarcinoma (1); hypogonadism (1); infection (1); movement disorder (1); neurodegenerative disease (1); Obesity (1); retinal degeneration (1).